SLC51B (SLC51 subunit beta)
Description:
Essential component of the OST-alpha/OST-beta complex, a heterotetramer that acts as the intestinal basolateral transporter responsible for bile acid export from enterocytes into portal blood. The OST-alpha/OST-beta complex efficiently transports the major species of bile acids (taurocholate). Taurine conjugates are transported more efficiently across the basolateral membrane than glycine-conjugated bile acids (By similarity). In the complex, SLC51B/OST-beta promotes the transmembrane translocation of bile acids. Can also transport steroids such as estrone 3-sulfate and dehydroepiandrosterone 3-sulfate, therefore playing a role in the enterohepatic circulation of sterols. Able to transport eicosanoids such as prostaglandin E2 (By similarity).
Synonyms: OSTB; OSTbeta; SLC51A1BP; PBAM2
Tractability: Antibody: UniProt places it where antibodies can reach, with high confidence; its Gene Ontology location is reachable by antibodies, with high confidence; UniProt predicts a signal peptide or a membrane-spanning region.
Gene: Protein-coding gene on chromosome 15 (65,045,387 to 65,053,397, forward strand). Ensembl gene ENSG00000186198.
Subcellular location: Basolateral cell membrane
Subcellular location (Human Protein Atlas): Mitochondria; Vesicles
Pathways (Reactome):
Metabolism: Recycling of bile acids and salts
Gene Ontology:
Molecular function: bile acid transmembrane transporter activity; protein binding; protein heterodimerization activity; transmembrane transporter activity
Biological process: bile acid secretion; bile acid and bile salt transport; transmembrane transport
Cellular component: basolateral plasma membrane; plasma membrane; membrane; protein-containing complex
Genetic constraint (gnomAD): Loss-of-function variants: 6 observed, 6.92 expected, observed/expected ratio (o/e) 0.87, 90% interval 0.47 to 1.64. That is too few expected variants to judge how well the gene tolerates losing a copy. Missense variants: 150 observed, 147.1 expected, observed/expected ratio (o/e) 1.02, 90% interval 0.89 to 1.17. Synonymous variants: 61 observed, 53.53 expected, observed/expected ratio (o/e) 1.14, 90% interval 0.93 to 1.41.
Homologues: Orthologues: chimpanzee SLC51B (99% identical), macaque SLC51B (95% identical), pig SLC51B (66% identical), rabbit SLC51B (66% identical), dog SLC51B (64% identical), mouse Slc51b (63% identical), rat Slc51b (59% identical), guinea pig SLC51B (56% identical).
Diseases named in the same sentence as SLC51B in open-access papers:
SLC51B is named in the same sentence as 15 diseases in open-access papers, as found by Europe PMC text mining. Sharing a sentence is not in itself a finding about the gene and the disease. The quoted sentences say what the papers report.
cholestasis (8 papers, 2014 to 2025). Impairment of the bile flow caused by obstruction within the liver, or outside the liver in the bile duct system. "It is highly induced in chenodeoxycholate-treated sandwich-cultured human hepatocytes, and OSTβ (SLC51B) deficiency presents with features of cholestasis." (PMID 36678658, 2022). "Recently, a homozygous single nucleotide deletion in organic solute transporter-β (OSTβ/SLC51B) was demonstrated to cause congenital diarrhea and cholestasis." (PMID 30367658, 2018).
Hepatic steatosis (2 papers, 2020 to 2022). Steatosis is a term used to denote lipid accumulation within hepatocytes. "LGALS3, SLC51B and SPP1 expression were in close association with the outcome of hepatic steatosis in both experimental approaches." (PMID 35046474, 2022). "Treatment with the clinical candidate, obeticholic acid reversed the hepatic steatosis phenotype and transcriptomic analysis confirmed the selective activation of FXR target genes including upregulation of FGF19 and PLIN1 and downregulation of SLC51B and CYP7A1 genes by OCA." (PMID 33334026, 2020).
liver disease (2 papers, 2022 to 2023). "The human blood side export carrier SLC51B was upregulated, suggesting that the principle of increased sinusoidal export may also be active in chronic human liver disease." (PMID 38053838, 2023).
liver cancer (1 paper, 2022). An epithelial or non-epithelial malignant neoplasm that arises from the liver. "SLC51B is involved in the intestinal reclamation of bile acids and steroids and eicosanoid metabolism, promoting liver cancer cell proliferation and suppressing apoptosis, which is associated with stemness." (PMID 35814473, 2022).
tumor (3 papers, 2021 to 2025). "Finally, analysis using two-way ANOVA revealed that among all clinical and histopathological data, only grade significantly affected expression of SLC51B gene with lower levels seen in high-grade tumours." (PMID 33917029, 2021). "Interestingly, gene SLC51A was up-regulated, while gene SLC51B was about 2-fold down-regulated in EC versus control tissue from patient with FIGO stage IA, low-grade tumour and tumour with ≤50% invasion into myometrium, which may affect the levels of the active OST heterodimer." (PMID 33917029, 2021).
cancer (1 paper, 2021). A tumor composed of atypical neoplastic, often pleomorphic cells that invade other tissues. "Six additional genes (SLC10A6, SLC22A1, SLC51A, SLC51B, SLCO1C1, SLCO4C1) were included to finally examine the expression of 15 genes encoding E1-S transporters in the total of 36 pairs of cancer and adjacent control tissue." (PMID 33917029, 2021). "There are very limited data available about expression of SLC51B and SLC51A in cancer." (PMID 33917029, 2021).
SLC51B also shares sentences with these, for which no sentence is quoted: colon cancer (3 papers); hepatocellular carcinoma (2); cholangiocarcinoma (1); colorectal cancer (1); endometrial cancer (1); Endotoxemia (1); gallstones (1); liver fibrosis (1); Obesity (1).